EGFR (epidermal growth factor receptor)
Diseases named in the same sentence as EGFR in open-access papers (continued):
Sharing a sentence is not in itself a finding about the gene and the disease.
glioma (continued). "Given the high occurrence of this mutation and the selectivity of Jak2 inhibitors for EGFRvIII-positive glioma cells, stratifying patients by EGFR mutation status may be an important factor in assigning Jak2 inhibitor therapy." (PMID 25162558, 2014). "We further hypothesize that the IL-1 expressing gliomas might be separate from those with EGFR mutation/amplifications." (PMID 25054228, 2014). "EGFR overexpression in gliomas is invariably associated with EGFR gene amplification." (PMID 23630597, 2013). "Moreover, we demonstrate that mice derived from crosses between these overexpressors and those carrying a GFAP-driven constitutively active EGFR variant transgene harbor more aggressive, higher-grade gliomas consistent with hyperactivated mTORC2 signaling." (PMID 23077666, 2012). "To examine whether and how variants in the EGFR gene contribute to glioma susceptibility, we evaluated nine tagging single-nucleotide polymorphisms (tSNPs) of the EGFR gene in a case–control study from Xi'an city of China (301 cases, 302 controls)." (PMID 22662167, 2012). "However, after a strict Bonferroni correction analysis was applied, the significance level of the association between EGFR tSNPs and risk of glioma was attenuated." (PMID 22662167, 2012). "This study has provided further evidence that the histological transformation and progression of gliomas may be associated with the inactivation of the EGFR and MGMT genes." (PMID 22264301, 2012). "Association between EGFR tSNP genotypes and the risk of glioma." (PMID 22662167, 2012). "Together, these findings indicate that ethnic differences among the EGFR gene variants may affect the development of glioma in diverse populations." (PMID 22662167, 2012). "There are three published GWAS to date that have identified eight different loci associated with glioma risk, including variants annotating key genes in glioma progression, such as the epidermal growth factor receptor (EGFR), and the tumor suppressor gene CDKN2A (alias p14, p16, and ARF)." (PMID 23236348, 2012). "The epidermal growth factor receptor (EGFR) is overexpressed or mutated in glioma." (PMID 24212795, 2011). "For example, 9 causal subnetworks are enriched with epidermal growth factor receptor signaling pathway that has anti-apoptotic properties and may enhance proliferation, invasion, and migration of glioma cells." (PMID 21390271, 2011). "Deregulation of EGFR by over-expression or constitutive activation promotes tumor processes including angiogenesis and metastasis and is associated with poor prognosis in many human malignancies including glioma, lung and breast cancer." (PMID 21915281, 2011). "Recently, several novel glioma-specific missense mutations in the ECD of the EGFR were identified." (PMID 24212795, 2011). "Glioma-associated antigens targeted by immunotherapeutic approaches include cell adhesion molecules, matrix proteins, and growth factor receptors, such as tenascin, wild-type epidermal growth factor receptor, its glioma-associated variant, epidermal growth factor receptor variant III, and GPNMB." (PMID 20809959, 2010). "However, in high-grade glioma, Rb loss co-occurs with EGFR and PTEN mutations, implying that these mutations cooperate to promote gliomagenesis." (PMID 19214224, 2009). "Recently a gene signature generated from autocrine platelet-derived growth factor (PDGF) signaling in gliomas has been used to classify gliomas, and it was shown that EGFR amplification and PTEN mutation/10q LOH were largely enriched in the cluster showing weak autocrine PDGF signaling." (PMID 19192267, 2009). "Our findings further verified the clinical implications of EGFR Amp in diffuse gliomas, and suggested future research should be undertaken on its association with other molecular alterations to offer more precise diagnosis, treatment and prognostic prediction of glioma." (PMID 38595969, 2024).
glioma (continued). "Regarding protein biomarkers, the growth factor receptor EGFRvIII (a variant form of EGFR) stands out among the glioma-specific oncogenes; it is one of the most studied tumor-specific proteins, since the mutant receptor is present in EVs secreted by glioma cells." (PMID 39194524, 2024). "Moreover, to further investigate whether ERK5 could influence the primary tumor cell growth, we collected PDCs from patients with different EGFR mutational status (Glioma#8, #14: both EGFR mutations and amplifications; Glioma#12, #22: WT)." (PMID 36720864, 2023). "Moreover, EGFR alteration has been proposed to have immunologic roles in GBMs; EGFR mutation governs the vascular and immune microenvironments by mediating the trans‐differentiation of glioma stem cells into pericytes." (PMID 37537946, 2023). "Moreover, within patients with EGFR-amplified glioma, patients harbored EGFR-mutant showed worse prognosis, compared to EGFR-wt patients, implying EGFR mutations and amplifications might have superimposed impacts on downstream biological processes." (PMID 36720864, 2023). "Our findings imply EGFR mutational status might relevant to the further conduct and planning of clinical trials investigating the therapeutic value of immune modulatory treatment strategies in glioma patients." (PMID 36720864, 2023). "For example, glioma cells overexpressing oncogenic EGFRvIII, a constitutively active deletion mutant of the ligand-binding domain, drive the release of pathogenic EV subsets that carry increased oncogenic EGFR and invasiveness-related proteases and adhesion proteins." (PMID 37823055, 2023). "Therefore, downregulation of the EGFR expression could cause apoptosis and inhibit proliferation in glioma cells." (PMID 35903366, 2022). "Furthermore, it is essential for researchers in different populations to perform association studies of EGFR variants with glioma samples isolated from local population, as glioma-associated genetic variants may vary by ethnicity." (PMID 36347915, 2022). "However, EGFR variants associated with gliomas in the Korean population remain unstudied." (PMID 36347915, 2022). "Additionally, EGFR-ht2 was associated with an increased risk of glioma (OR = 1.32, P = 0.02)." (PMID 36347915, 2022). "Within IDH wild-type gliomas, the higher hypoxia associated with EGFR amplification may be explained by two mechanisms: the translational up-regulation of EGFR induced by hypoxic microenvironment and the enhanced oncogenic pathways downstream to increased EGFR activation." (PMID 35626127, 2022). "Finally, our tissue-specific analyses highlight five candidate tissues (cerebellum, cortex, and the putamen, caudate and nucleus accumbens basal ganglia) and four genes (JAK1, STMN3, PICK1 and EGFR) which had causal evidence for affecting glioma risk in further research." (PMID 33504897, 2021). "Furthermore, EGFR alterations have been associated with the recruitment of immune cells in gliomas." (PMID 32570988, 2020). "In addition, ERRFI1 was reported to have common focal deletions in analysis of 1,057 glioma cases while it could encode Mig6, a feedback inhibitor to block the activation of EGFR." (PMID 33117083, 2020). "It gave us one hint that frequency of EGFR mutation might be notably underestimated, and it also might be the potential explanation of some rapid progressed lower-grade glioma (histopathological diagnosis) which might essentially be higher-grade glioma in molecular level." (PMID 31801484, 2019). "Additionally, molecular analysis of tunicamycin-treated tumors has revealed reduced levels of EGFR and Met in gliomas, suggesting that inhibition of N-linked glycosylation might be a novel therapeutic strategy against cancer." (PMID 31533338, 2019). "In addition, EGF prevents NSC differentiation, and EGFR signaling is associated with enhanced cellular proliferation, survival, and infiltration in the adjacent parenchyma, similar to the events observed in high-grade gliomas." (PMID 31482066, 2019).
glioma (continued). "Although changes in a number of genetic factors, such as PTEN, VEGF, and EGFR, are associated with the pathogenesis of glioma and the chemoresistance of glioma cells to TMZ, the molecular biology of chemoresistance of glioma cells to TMZ is still largely unknown." (PMID 28831025, 2017). "Therefore, IDH1, PTEN and EGFR showed mutational exclusivity in glioma." (PMID 29046615, 2017). "Therefore, it is logical to hypothesize that functional genetic polymorphisms involving EGF or EGFR may predispose to glioma development." (PMID 24740103, 2014). "Thus, irrespective of the cell of origin, an NSC or a differentiated astrocyte, events that lead to loss of p16INK4a and p19ARF and constitutive signalling via EGFR, possibly leading to a loss of differentiation, eventually provoke highly malignant (high-grade) glioma." (PMID 23998913, 2013). "Exposure of human microglial cells (HMC3) to EVs released from GW4869-treated and control glioma cells triggered distinctive changes in cellular proteome including transfer of EGFR." (PMID 41953752, 2026). "In high-grade gliomas with a defined mutation (e.g., BRAF mutation, EGFR mutation), patients receiving targeted therapy (tyrosine kinase inhibitor) had a higher overall survival (OS) rate compared to those receiving conventional chemotherapy." (PMID 41596345, 2026). "Our study identified HBEGF, a potent mitogen expressed on plasma membrane and key regulator of EGFR signaling, as an accessible target and an important player driving glioma phenotypic plasticity." (PMID 41181988, 2026). "Here we employed a series of human glioma cell lines to test the content and distribution of oncogenic epidermal growth factor receptor (EGFR) including its mutant (EGFRvIII) among different subsets of tumour-derived EVs." (PMID 41953752, 2026). "Concurrently, high-risk gliomas demonstrated hyperactivation of pro-tumorigenic pathways (e.g., mTOR, MAPK) and frequent EGFR amplification." (PMID 41756290, 2026). "While mutations in IDH are rare in primary GBM that show alterations in EGFR and PTEN, these mutations are more frequently observed in lower-grade gliomas and in those that progress to higher-grade tumors." (PMID 40223032, 2025). "The role of the TME in glioma development is primarily associated with the release of cytokines such as IL-6, platelet-derived growth factor (PDGF), VEGF, and epidermal growth factor receptor (EGFR)." (PMID 40136652, 2025). "In turn, the cancer phenotypes observed in the Drosophila glioma model were found to rely on crucial downstream effectors of EGFR and PI3K signaling including the Tor, Myc, G1 Cyclins-Cdks, and Rb-E2F pathways." (PMID 40806617, 2025). "Research on MiR-34a has shown that it can affect the expression of PD-L1 and epidermal growth factor receptor (EGFR) to have an antitumor effect on glioma cells." (PMID 40727443, 2025). "EGFRvIII, a mutant form of the epidermal growth factor receptor (EGFR), is commonly expressed in glioma and prevalent in ~50% of GBM cases." (PMID 40661781, 2025). "In contrast, EGFR amplification is characterized by greater temporal heterogeneity, making diagnosis inherently challenging, particularly in recurrent gliomas." (PMID 40197845, 2025). "In glioma, when cells are stimulated by hypoxia or EGFR activation, PGK1 can translocated in mitochondria to activate PDHK1 phosphorylation, suppressing the TCA cycle ultimately promoting tumour growth." (PMID 40534132, 2025). "It was found that both 131I-labeled peptides exhibited high specificity for EGFR, favorable biodistribution, and promising potential for use in glioma cells." (PMID 40558363, 2025). "In particular, a radiogenomic study based on the evaluation of glioma texture analysis extracted from T2WI succeeded in predicting EGFR levels in LGGs with an AUC of 0,95." (PMID 40870498, 2025).
glioma (continued). "The JNK activation has been shown to have a crucial role in the tumorigenesis of gliomas, possibly through the EGFR-mediated signaling pathway and maintenance of stemness." (PMID 41226237, 2025). "The unique 14 amino acids at the C-terminus of C-E-Cad bind to the EGFR CR2 domain, activating epidermal growth factor receptor (EGFR) and maintaining the tumorigenicity of glioma stem cells." (PMID 40034125, 2025). "Herein, we describe the study of the lipophilic properties of carborane-containing Erl analogs 1–7 and examine their correlation with cytotoxicity against glioma cells and EGFR-inhibitory activity." (PMID 41304996, 2025). "This study first unveils a non-classical mechanism through which Dio induces apoptosis via the EGFR–CASP3 axis in gliomas, providing novel insights for developing therapeutics targeting EGFR signaling networks." (PMID 40391080, 2025). "An evaluation of epidermal growth factor receptor (EGFR) signaling via EGF stimulation of glioma cell lines resulted in only a slight increase (1.3- to 1.6-fold) in MT5-MMP mRNA levels." (PMID 40867559, 2025). "Glioma, non-small cell lung cancer, head and neck, breast, colorectal, ovarian, prostatic and pancreatic cancers are known to all exhibit increased EGFR activity, which is considerably beneficial to survival and growth of these cancer cells." (PMID 39888904, 2025). "Exosomal microRNA‐148a‐3p promotes tumour angiogenesis by inhibiting ERRFI1 activation of the EGFR/MAPK signalling pathway in glioma." (PMID 39950738, 2025). "To date, there are no data in PubMed (except our first attempt) describing the application of anti-EGFR complexes with either Ap-DOX or ACCO-DOX for glioma treatment." (PMID 40943631, 2025). "In conclusion, we demonstrated that alisertib treatment elevated B7-H3 expression in glioma cells by increasing EGFR activity." (PMID 39928563, 2025). "The downregulation of LOX is unexpected, given its established role in enhancing glioma invasiveness via extracellular matrix crosslinking and remodeling through enhancing epidermal growth factor receptor (EGFR) signaling." (PMID 40835683, 2025). "Mechanistically, AURKA elevated B7-H3 expression by promoting epidermal growth factor receptor (EGFR) phosphorylation, which was validated in glioma cell lines and primary GBM cells." (PMID 39928563, 2025). "Their ability to regulate EGFR and its various downstream signaling pathways as well as other receptor-tyrosine kinases offers an interesting target for glioma treatment." (PMID 41201961, 2025). "Our results demonstrated that scutellarin and lidocaine also separately downregulated the EGFR protein level of glioma cells in dose-dependent manner." (PMID 39888904, 2025). "Gefitinib, which inhibits the epidermal growth factor receptor, is under study for its potential as a glioma‐targeted therapy combined with nanoparticles." (PMID 40561176, 2025). "Following correction for multiple comparisons, FA in the left AF (p = 0.025) and in the left FAT (p = 0.020) was found to be significantly lowered in EGFR amplified glioma." (PMID 40941753, 2025). "Kyoto Encyclopedia of Genes and Genomes (KEGG) pathway analysis further confirmed that these proteins were closely associated with core cancer pathways such as “Glioma,” “PI3K-Akt signaling pathway,” and “EGFR tyrosine kinase inhibitor resistance”." (PMID 41373831, 2025).
glioma (continued). "The combination of Kae and Gef (gefitinib) results in a more pronounced inhibition of glioma cell proliferation compared to either treatment alone, and Kae further enhances the inhibition of EGFR and SRC phosphorylation when used alongside Gef." (PMID 41009025, 2025). "Specifically, GOLPH3 was found to promote glioma progression by inhibiting Rab5-mediated endocytosis and degradation of the epidermal growth factor receptor (EGFR)." (PMID 39944595, 2025). "According to the WHO 2021 Classification of Gliomas, EGFR amplification and CDKN2A/B HD play crucial roles in integrated malignancy diagnosis." (PMID 40786409, 2025). "Our results revealed that alisertib treatment upregulated B7-H3 protein expression by activating EGFR signaling in glioma cells." (PMID 39928563, 2025). "From a methodological perspective, this study establishes the feasibility of the multi-marker detection approach (EGFR+/GFAP+/CD45-) for reliable identification of glioma-derived CTCs." (PMID 40214852, 2025). "Early experimental work demonstrated that the TGF-α/EGFR autocrine loop promotes glioma cell proliferation and survival, and subsequent studies confirmed EGFR–TGF-α signaling as a hallmark pathway in human gliomas arget." (PMID 41267963, 2025). "EGFR, FAT4, and BCOR were the three features associated with 64% ACC using the TCGA-UCI glioma grading set aimed at tumor grading." (PMID 40362575, 2025). "The splicing of a brain-enriched cassette exon in the tumor suppressor ANXA7 is mediated by PTBP1, which subsequently enhances EGFR signaling during glioma progression." (PMID 40303323, 2025). "An in-depth study investigating this relationship demonstrated a novel role for TMED2 in EGFR signaling, a process which has been shown to be crucial for promoting glioma development." (PMID 40497947, 2025). "Studies show that CRNDE expression regulates glioma cell growth and promotes tumor progression by positively regulating the EGFR signaling pathway." (PMID 40130175, 2025). "These carboranes generally exhibited improved cytotoxicity against glioma cell lines compared with the parent compound erlotinib and additionally showed varying degrees of EGFR inhibition." (PMID 41304996, 2025). "For example, pediatric gliomas are enriched for MAPK pathway alterations and gene fusions, while adult gliomas more commonly harbor IDH mutations, TERT promoter mutations, and EGFR amplifications." (PMID 41284071, 2025). "In Olig2-deficient glioma models, the downregulation of PDGFRA signaling is accompanied by feedback upregulation of the EGFR pathway to sustain tumor growth." (PMID 40428395, 2025). "EGFR alterations represent one of the most common molecular hallmarks of gliomas, however, the contribution of its upstream ligand TGFA to gliomagenesis has remained largely unexplored." (PMID 41267963, 2025). "It inhibits proliferation, invasion and angiogenesis and promotes apoptosis of glioma cells by negatively regulating EGFR and VEGFA." (PMID 41201961, 2025). "Regarding EGFR amplification, the proportion of EGFR+ tumor cells in EGFR‐amp gliomas was higher than in EGFR‐wild‐type gliomas." (PMID 40264576, 2025). "Transduction of neural stem cells (NSCs) or astrocytes with constitutively active EGFR leads to tumorigenic phenotypes of high-grade gliomas." (PMID 41145413, 2025). "In another study, CD109 expression was found to promote the progression of glioma and tumour metastasis and resistance via the EGFR pathway expression." (PMID 40227788, 2025). "After the animals were euthanized, glial tumor tissue was taken for IHC tests to confirm EGFR expression." (PMID 41473440, 2025).